IL6 (interleukin 6)
Diseases named in the same sentence as IL6 in open-access papers (continued):
Sharing a sentence is not in itself a finding about the gene and the disease.
cancer (continued). "Of all the differentially expressed genes, secreted signaling proteins Tgfb2, Il-6, Cxcl1, and Ctgf and metallopeptidases Mmp13, Adamts4, and Adamts5 were of particular interest, as these genes have previously been shown to play a role in regulating cancer migration and invasion and bone remodeling." (PMID 27600237, 2015). "Considering that the unity was not included by above 95% CIs, it is safe to the reject the null hypothesis of none causal relevance between circulating IL-6 and certain cancer subtypes." (PMID 26096712, 2015). "Contrary to the previous studies, the current researchers could not detect any association between serum IL-6 levels and cancer stage in OTSCC." (PMID 26082902, 2015). "The presence of IL-6 in tissues is not an unusual occurrence, but its production can lead to uncontrolled exposure and subsequent chronic inflammation, and they are strongly associated with many types of cancer." (PMID 27034686, 2015). "Finally, miR-34a mimetics may be used to repress s-IL-6R expression and consequently IL-6 trans-signaling, to treat inflammatory diseases and cancer." (PMID 26091352, 2015). "However, recent reports indicate that autocrine induction of IDO by IL-6 is STAT3-dependent in some cancer cells or in myeloid suppressor cells, suggesting that cytokines may induce IDO expression through different STAT pathways." (PMID 26657115, 2015). "We examined the IL-6/STAT3 signaling pathway to determine whether it plays an important role in macrophage-induced activation of cancer stem cells after co-culture with apoptotic cancer cells." (PMID 26016502, 2015). "However, when we examined the mRNA levels and supernatant content of inflammatory cytokines in hUC-MSCs and IL-6-hUC-MSCs, we found that the levels of several cancer-promoting cytokines, including CCL5, PDGF-BB, MCP-1 and TNFα, were markedly downregulated in the IL-6-hUC-MSCs." (PMID 25483835, 2015). "Similarly, the role of IL-6 has been well studied in several cancer types." (PMID 25868978, 2015). "Furthermore, the residual cancer cells in the resected specimens expressed IL-6, IL-6R and p-STAT3." (PMID 25761055, 2015). "Cancer pain can be caused by different mediators: immune system cells infiltrating the tumor: neutrophils, T cells, and macrophages secrete prostaglandins, endothelin, TNF-α, Transforming Growth Factor (TGF), IL-1 and IL-6, Epidermal Growth Factor (EGF), and Platelet Derived Growth Factor (PDGF)." (PMID 26538839, 2015). "Moreover, because interleukin 6 plays an active role in other diseases such as cancer, further studies of this new pathway may help explain how this molecule encourages cancers to progress and/or spread around the body." (PMID 25974216, 2015). "Moreover, it was suggested that treatments that could impair the increase in IL-6 in adipose tissue could ameliorate cachexia in cancer." (PMID 26508818, 2015). "Indeed we found that SDE-genes identified in previous step are related to STAT3 pathways including genes involved in cell cycle progression (Cyclin D1, D2, and c-Myc), cell survival (Bcl-xL, Bcl-2, Mcl-1), angiogenesis (HIF1α, VEGF), cancer inflammation (NF-KB, IL-6)." (PMID 26056083, 2015). "Therefore, c-Jun activation is mediated by IL-6-increased cancer metastasis and ICAM-1 expression." (PMID 24398980, 2014). "Thus, blocking IL-6 signaling seems to be a rational direction to repress cancer growth." (PMID 24664372, 2014). "Various studies have identified IL-4 or IL-6, produced by enterocytes and lamina propria myeloid cells, to a play critical role in both the survival and proliferation of pre-malignant intestinal epithelial cells as well as resistance of cancer stem cells to therapeutic treatments." (PMID 24970802, 2014). "Thus, it is intriguing that MUC2 may induce a systemic antitumor immune response and may have therapeutic value in the treatment of IL-6-secreting cancers." (PMID 25322805, 2014).
cancer (continued). "Based on the fact that IL-6 and its receptors are overexpressed in various cancer types, these mutations are speculated not to be loss-of-function mutations, with the complex being turned on constitutively." (PMID 24670367, 2014). "Moreover, the level of IL-6 is positively correlated with poor prognosis in different cancers." (PMID 24885636, 2014). "However, the expression of the membrane-bound IL-6R may increase in cancer cells and alternative mechanisms may induce detrimental activation of the IL-6 system." (PMID 24886605, 2014). "Therefore, taking into account the pro-cancer roles of IL-6, it is not surprising that elevated serum levels of IL-6 and sIL-6R have been associated to chemoresistance with poor clinical outcome in different human cancers." (PMID 23517603, 2013). "Therefore, we hypothesized that IL-6 reduction may improve efficacy of vaccination against TNBC cancer through improved T-cell responses." (PMID 24156030, 2013). "Therefore, the inhibitory effect of JTT on IL-6 elevation might be beneficial for controlling cancer progression." (PMID 23840274, 2013). "Interestingly, IL-6 has been shown to promote changes in DNA methylation during cancer development." (PMID 23991173, 2013). "Its production is induced by proinflammatory cytokines such as Interleukin-6 (IL-6), IL-8, and tumour necrosis factor alpha (TNF-α) and its levels have been positively correlated with weight loss, anorexia-cachexia syndrome, extent of disease, and recurrence in many cancer types including CRC." (PMID 23840958, 2013). "Therefore, IL-6R overexpression, coupled with enhanced IL-6/STAT3 signaling may facilitate the malignant transformation of EBV-infected premalignant NPE cells into cancer cells, and enhance malignant properties of NPC cells." (PMID 23658720, 2013). "Therefore, blocking of IL-6 signaling could be beneficial to cancer patients undergoing EGFR-TKI treatment for reducing the risk of its unfavorable effects." (PMID 23592411, 2013). "However, whether this capacity to overproduce IL-6 is constitutive in metastatic cells and/or regulated by cancer cell-independent mechanisms is unknown." (PMID 23517603, 2013). "Thus, we assumed that IL-6 derived from cancer cells could affect the metastasis of cancer cells through inflammatory cell, including MDSC, recruitment." (PMID 24021059, 2013). "In addition, a recent report indicated that HVJ-E could induce cytotoxic T cells against cancers and inhibit regulatory T cells by IL-6 expression in dendritic cells." (PMID 24007528, 2013). "Further, we found that EGFR blocking could increase IL-6 in the cancer cells." (PMID 23592411, 2013). "Importantly, it has been demonstrated that PIM1 gene expression is induced by IL-6 via the JAK/STAT signaling pathway and that T. vaginalis–induced IL-6 likely provides an additional molecular link between exposure of human PECs to T. vaginalis, stress, and cancer induction." (PMID 22912571, 2012). "Therefore, this raises the question of whether signaling involving SOCS3 may crosstalk with myogenic pathways under chronic IL-6 stimulation during cancer cachexia." (PMID 22361433, 2012). "Therefore, a complex network of cytokine signaling is involved in the pathogenesis of cancer cachexia and cytokines such as IL-6, may play a dominant role." (PMID 22361433, 2012). "Therefore, we aim to determine whether the IRP and other inflammatory markers (Interleukin-6 (IL-6); Tumour necrosis factor-α (TNF-α); C-reactive protein (CRP)) are associated with wellbeing/mortality in older cancer patients." (PMID 22026575, 2011). "This situation may explain high IL-6 levels related with cancer progression and invasion." (PMID 20920199, 2010). "As IL-6 produced in cancer cells can freely diffuse across the cell membrane into the stroma, the loss of tumoral sIL-6R expression may reflect either decreased production of sIL-6R itself or increased consumption of sIL-6R by enhanced IL-6/sIL-6R affinity in the cancer stroma." (PMID 20823887, 2010).
cancer (continued). "Thus, the three major down-stream pathways of IL-6 might crosstalk in the regulation of IL-6 autocrine production in cancer cells." (PMID 21122157, 2010). "Thus, drug resistant cancer cells are ideal models for studying IL-6 autocrine production." (PMID 21122157, 2010). "In addition to Jak2/Stat3 pathway, PI3-K/Akt and MEK/Erk could also contribute to the regulation of IL-6 autocrine production in cancer cells." (PMID 21122157, 2010). "The results suggest that targeting c-Met signaling may attenuate cell proliferation induced by other growth factors such as IL-6, and may therefore represent a novel approach to cancer treatment also in cancers that at first sight seem independent of c-Met signaling." (PMID 19187270, 2009). "The pro-inflammatory cytokines interleukin (IL)-1β, IL-6, tumour necrosis factor (TNF)-α and interferon (IFN)-γ (also called pro-cachectic cytokines) are thought to be responsible for the metabolic changes associated with cancer cachexia through different mechanisms." (PMID 19018259, 2008). "These known NF-κB target genes, such as IL6, IL8, BIRC2 (clAP-1), ICAM1, YAP1, CDKN1A (p21), CSF2, CCDN1, IL1A, IL1B, and so on, include many that have been independently confirmed to be differentially expressed and pathologically implicated in HNSCC and other cancers." (PMID 18334025, 2008). "In the cancer patients who had detectable circulating preoperative C-reactive protein concentrations (n=41), log-transformed concentrations of C-reactive protein were significantly correlated with interleukin-6 (r2=0.62, P<0.001) and interleukin-10 (r2=0.33, P<0.001)." (PMID 17003778, 2006). "In the cancer patients who had detectable circulating postoperative C-reactive protein concentrations (n=35), log-transformed concentrations of C-reactive protein were significantly correlated with those of interleukin-6 (r2=0.66, P<0.001) and interleukin-10 (r2=0.33, P<0.001)." (PMID 17003778, 2006). "Therefore, if in cancer patients C-reactive protein was stimulated by factors other than interleukin-6, then it might be expected that the relationship between interleukin-6 and C-reactive protein would be less strong than that in patients with benign disease." (PMID 15505624, 2004). "IL-6 that could be produced by cancer cells is up-regulated by n-BT." (PMID 10408408, 1999). "Synergism of YAP/TAZ with Wnt/β-catenin and Notch pathways promotes the maintenance of cancer stem cells (CSCs) and EMT, and collaboration with STAT3 potentiates proinflammatory cytokines, like IL-6." (PMID 41476776, 2026). "Studies have shown that IL-6 levels and the STAT3 signaling pathway are markedly increased in the skeletal muscle of cachexia mice induced by C26 cancer cells and that the inhibition of STAT3 alleviated muscle wasting." (PMID 41526343, 2026). "Some inhibitors targeting IL-6 or the JAK/STAT3 pathway have been tested and show promising results, including slowing or stopping cancer progression." (PMID 41596531, 2026). "In addition, the downregulation of IL6-JAK-STAT3 signaling in the high-risk samples was inconsistent with the enrichment of M2-type macrophages, which indicates that non-classical activation of STAT3, such as through the EGFR or inflammasome pathway, is the dominant driver of cancer." (PMID 41601652, 2026). "Together, CAFs and TAMs interact with cancer cells to activate pathways such as the TGF-β, IL-6, and PI3K/AKT pathways, which drive resistance to therapy." (PMID 41590379, 2026). "Here, The effects of TGF-β1, IL-6, and HGF cytokines on the development of TNT conduits between adjacent cancer cells, as well as the effects of oseltamivir phosphate (OP) treatment, were measured using fluorescent microscopy and image analysis software." (PMID 41750361, 2026). "Network analysis highlighted STAT3, EGFR, SRC, IL-6, and AKT1 as key hub targets, with enrichment in cancer-related, EGFR resistance, and PI3K-Akt pathways." (PMID 42123459, 2026).
cancer (continued). "The review further highlights the strain-specific nature of detoxification, the impact of mycotoxin-induced dysbiosis on short-chain fatty acid production and inflammation, and the modulation of cancer-related pathways including NF-κB, STAT3, and IL-6." (PMID 41821854, 2026). "These activated CAFs, in turn, upregulate the expression of IL6, CXCL12, and VEGFA in response to cancer‐derived TGFβ stimulation; ultimately enhancing metastasis and contributing to therapy resistance." (PMID 40968783, 2026). "AMK polysaccharide • Enhanced phagocytosis by BMDMs• Activated expression and secretion of immunomodulatory factors (IL-6, IFN-λ, TNF-α, and NO) in BMDMs through TLR4 and MyD88The TLR4/MyD88 pathway plays a vital role in anti-cancer effects of AMK." (PMID 40144663, 2025). "IL-6 activates STAT3 via the MAPK-STAT3 phosphorylation pathway, which supports cancer cell proliferation, survival, invasion, and metastasis." (PMID 40708946, 2025). "In hepatocellular carcinoma, TAMs release IL-6 and VEGF, stimulating cancer cell proliferation and vascular growth." (PMID 41311372, 2025). "In cancer cells, both SA and Dox increased pro-inflammatory cytokines (TNF-α, IL-6, IL-1β) and NO, likely contributing to an acute inflammatory response that facilitates immunogenic cell death." (PMID 41304843, 2025). "M1 macrophages have anti-cancer and pro-inflammatory effects, such as phagocytosis, lysis, induction of apoptosis via cytokines, tumor necrosis factor (TNF), IL-6, IL-12, and IL-23, and the ability to enhance CD8+ T cells." (PMID 40872475, 2025). "In support of this, broad-spectrum antibiotics in a non-cancer context (obese mice) have been shown to reduce circulating LPS and lower systemic TNF-α/IL-6 levels." (PMID 40572244, 2025). "While specific evidence supporting these interventions in HL survivors is lacking, cognitive behavioral therapy improves sleep hygiene, reduces proinflammatory cytokines (i.e., IL-6, TNF-α) and improves immune function in other cancer survivor populations." (PMID 41300993, 2025). "In cancer cachexia, components of the UPS are activated by the inflammatory cytokines TNF-α and IL-6 via the NF-κB and STAT3 pathways, which upregulate MuRF1 and atrogin-1 expression." (PMID 40869331, 2025). "Cytokines such as IL-1, IL-6, TNF, and others (TGF-β, IL-22, IL-11) interact with cancer cells, promoting signaling pathways (e.g., IKK-NF-κB, JAK-STAT3, MAPK-AP1) that support cancer progression." (PMID 39996799, 2025). "This blockade is one of the major mechanisms that promote cancer progression, and it occurs under cancer conditions and is influenced by tumor-derived factors such as VEGF, IL-6, and IL-1β." (PMID 40491907, 2025). "Monocytes and macrophages, the main tumor-infiltrating cells, produce cytokines like IL-1β, IL-6, IL-23, and TNF-α, playing a crucial role in cancer progression within an inflammatory context." (PMID 40430101, 2025). "Our simulations suggested that both severe cancer and immunosuppressed patients have decreased CD8 + T cells, elevated neutrophils, and IL-6 concentrations, and delayed IFN peaks." (PMID 40489562, 2025). "Irisin, oncostatin and SPARC have, for example, been shown to suppress colon and breast cancer growth, and IL-6 and SPARC play roles in the prevention of cancers by exercise." (PMID 41300368, 2025). "This long-term immunosuppressive state is likely triggered by the stimulation of M2 macrophages by cancer cells, which release cytokines such as TGF-β, IL-6, and IL-10, all of which can weaken the immune response." (PMID 40636413, 2025). "As a downstream pathway of the IL–6/STAT–3 axis, STAT–3 is a hot topic in cancer and inflammation research." (PMID 40005889, 2025).
cancer (continued). "Numerous studies have identified positive correlations between serum inflammatory biomarkers and cancer-related mortality, including CRP, IL-6, leukocytes, neutrophils, haptoglobin, albumin, and TNF." (PMID 40563468, 2025). "Epithelial cells undergo abnormal proliferation, while IL-6 and TNF-α activate the inflammation-to-cancer pathway, ultimately driving cellular carcinogenesis." (PMID 41415031, 2025). "STAT3 activity in CAFs induces the release of IL-6, TGF-β, and VEGF by cancer cells, promoting immunosuppression and metastasis)." (PMID 40136652, 2025). "In this secondary analysis of our randomized controlled CRBP-TS trial, we evaluated the effects of HOET on the cytokines IL-1ß, IL-2, IL-6, IL-10, IL-12p70, TNF-α, IFN-γ, and the mGPS of 145 cancer patients." (PMID 40498221, 2025). "CAF-derived cytokines, including IL-6, GM-CSF, and CXCL12, induced the differentiation and activation of myeloid-derived suppressor cells (MDSCs) and TAMs to favor cancer progression." (PMID 40447617, 2025). "For example, iCAF-derived IL-6 induces epithelial-mesenchymal transition (EMT) and cell proliferation of cancer cells." (PMID 40025612, 2025). "With respect to the diagnostic biomarkers, we detected significantly higher serum levels of CA125, HE4, IL-6, IL-8, G-CSF, SAA, MRP8/14, OPN, MMP9, and MMP2 in women with benign or malignant tumors than in healthy controls." (PMID 41149076, 2025). "A study examined the associations between circulating levels of the inflammatory markers IL-6, C-reactive protein (CRP), and TNF-α with overall cancer incidence as well as the incidence of cancers specific to certain sites (breast and prostate)." (PMID 40584290, 2025). "Following the same protocol as the immunofluorescence of cancer cells, RAW-Blue macrophages were treated with either TGFβ-1 (4.0 × 10−3 μg/mL), IL-6 (4.1 × 10−5 μg/mL), or HGF (5.97 × 10−4 μg/mL) and stained with E-cadherin, N-cadherin, and vimentin." (PMID 40227834, 2025). "We concentrated on the expression level of pro-inflammatory cytokines (IL-1, IL-6, and TNF-a) and HERV genes involved in neuro-inflammatory and cancer processes." (PMID 40143237, 2025). "In summary, SsnB exerts its anti-cancer effects by downregulating MyD88, p-ERK, and p-NFκB signaling, along with suppressing the pro-inflammatory cytokines TNF-α, IL-1β, and IL-6." (PMID 40143078, 2025). "AhR stimulates IL-6–dependent STAT3 signaling, which maintains IDO1 expression and thereby immunosuppression in several human cancers." (PMID 40789452, 2025). "Advanced stages of cancer are often characterized by elevated levels of cytokines such as TGF-β, known for its immunosuppressive properties, and IL-6, which has immunostimulatory effects." (PMID 41373438, 2025). "The role of the CRP is of significance, given that it has been identified as a potential mediator of carcinogenesis and cancer progression via the activation of the FcgRs/MAPK/ERK, FcgRs/NF-kB/NLRP3, and FcgRs/IL-6/AKT/STAT3 pathways." (PMID 40076898, 2025). "Actually, a possible mechanistic link between IL-6 and thrombosis in cancer has been hypothesized in a murine model, but, to the best of our knowledge, there are no studies investigating the relationships between IL-6 and both total and EV-associated TF in patients with cancer." (PMID 39858477, 2025). "In a related study, macrophages co-cultured with NRF2 active cancers were driven to an immunosuppressive M2 phenotype characterized by increased CD163 and Arg1 as well as diminished IL-6 and IL-1b." (PMID 40946102, 2025). "The modulation of IL‐6, IL‐8, and CXCL1 by KLK14 has potential implications beyond wound healing, particularly in cancer." (PMID 40621923, 2025).